USP7 (ubiquitin specific peptidase 7)
Diseases named in the same sentence as USP7 in open-access papers (continued):
Sharing a sentence is not in itself a finding about the gene and the disease.
neuroblastoma (29 papers, 2015 to 2025). Neuroblastoma (NB) is the most common solid, extracranial childhood tumor. "As further demonstrated by in vitro and in-cell assays, STIRUR 41 was able to inhibit both the enzymatic activity of USP-7 and its expression levels in neuroblastoma-related cells, thus laying an encouraging base for the blockade of USP-7 downstream signaling." (PMID 37298148, 2023). "Ubiquitin-specific protease 7 (USP-7; also known as HAUSP) has been demonstrated asana MYCN function regulator in neuroblastoma." (PMID 37298148, 2023). "For instance, USP7 deubiquitinates and stabilizes N-myc protein to promote neuroblastoma progression." (PMID 37081042, 2023). "Among them, we focalized our attention on the proteins involved in neuroblastoma development, namely, Ubiquitin specific protease 7 (i.e., USP-7), Nuclear RNA export factor 1 (i.e., NXF1), and Pescadillo homolog (i.e., PES1)." (PMID 37298148, 2023). "Given that in neuroblastoma patients the increased expression of USP7 seem to predict the worst clinical outcomes, P22077 was suggested to be a promising compound to be used as a treatment strategy." (PMID 34577547, 2021). "As an inhibitor of USP7, P22077 has been used to study the roles of USP7 in inflammatory response and neuroblastoma growth." (PMID 32516131, 2020). "A similar role of USP7 has also been found in gliomas, neuroblastoma, and ovarian cancer, and USP7 overexpression is correlated with the disease progression and poor survival of patients." (PMID 32300595, 2020). "Consistently, overexpression of USP7 in human neuroblastoma cells led to upregulation of N-Myc, which is in agreement to our findings of upregulated c-Myc in HEK293T cells after overexpression of USP7." (PMID 29899379, 2019). "To test whether MAGED1 associates with USP7 in human cells, we performed co-IP-MS of MAGED1 in two different human cell lines: human embryonic kidney 293 T (HEK293T) and neuroblastoma (SH-SY5Y) cells." (PMID 38123574, 2023). "N-MYC degradation by inhibitor P22077 (USP7 inhibitor) in neuroblastoma is one such example." (PMID 33613844, 2021). "The expression of USP7 is enhanced in patients of neuroblastoma with poorer prognosis." (PMID 33614505, 2020). "USP7 was shown to deubiquitinate N-Myc, thereby stabilizing it in human neuroblastoma cells." (PMID 29899379, 2019). "Novel, selective inhibitors of USP7, USP7-055, and USP7-797, have been developed recently for tumor therapy including MYCN-amplified neuroblastoma." (PMID 33614505, 2020). "Ubiquitin-specific protease 7 (USP7) regulates the stability and activity of N-MYC in neuroblastoma." (PMID 33614505, 2020). "In addition, the interaction between endogenous FBXO7 and USP7 was confirmed in HEK293 and human neuroblastoma SH-SY5Y cells." (PMID 37874827, 2023).
neuroblastoma (continued). "It would be beneficial to understand whether such a role also involves USP7 activity to deubiquitinate N-MYC especially in neuroblastoma with N-MYC amplification or antagonize TRIM32-mediated MYC ubiquitination and whether USP7 deubiquitinates c-MYC as well." (PMID 34178666, 2021). "USP7 has been identified as a critical regulator of Dox resistance across several cancer types, including HCC, pancreatic ductal adenocarcinoma (PDAC), and neuroblastoma (NB)." (PMID 38702734, 2024).
ovarian carcinoma (26 papers, 2015 to 2026). A malignant neoplasm originating from the surface ovarian epithelium. "Although overexpression of USP7 has been observed in several types of cancer cells, its association with ovarian cancer cells is unknown." (PMID 27780924, 2016). "Next, to further investigate the regulatory relationship among Sp1, USP7 and c-Myc, we co-transfected ovarian cancer cells with a Sp1-overexpression plasmid and siRNA targeting USP7." (PMID 41584043, 2026). "Several molecular factors have been implicated in ovarian cancer lymph node metastasis, including USP7, FAK, and the VEGFC-VEGFR3 signaling axis, all of which are associated with an increased incidence of lymphatic metastasis in ovarian cancer patients." (PMID 40109727, 2025). "To do this, we reduced CCDC6 protein levels in ovarian cancer cells using the USP7 inhibitor P5091 and evaluated sensitivity to various olaparib concentrations." (PMID 35964058, 2022). "Expression of deubiquitylase USP7 is reported to be a prognostic factor in osteogenic sarcoma, T-cell lymphoma and ovarian cancers." (PMID 32002017, 2020). "In terms of lymphatic metastasis, molecules including USP7, FAK, as well as the VEGFC-VEGFR3 interaction, are shown to associate with incidence of lymph node metastases of ovarian cancer." (PMID 31888563, 2019). "Over-expression of USP7 promotes cell invasiveness, whereas USP7 knock-down inhibits cell viability in ovarian cancer cells." (PMID 30319415, 2018). "Compared with the non-tumorigenic immortalized ovarian surface epithelial (IOSE) cells, several ovarian cancer cell lines exhibit higher USP7 expression." (PMID 27780924, 2016). "We demonstrated that ovarian cancer cells have higher USP7 expression than their normal counterparts." (PMID 27780924, 2016). "We provide evidence that USP7 is expressed at higher level in ovarian cancer cell lines and primary ovarian cancer cells." (PMID 27780924, 2016). "Collectively, these findings suggest that USP7 binds to and regulates c-Myc in ovarian cancer." (PMID 41584043, 2026). "Furthermore, co-immunoprecipitation (Co-IP) assays confirmed the physical interaction between USP7 and c-Myc in ovarian cancer cells." (PMID 41584043, 2026). "USP7 overexpression extended the half-life of c-Myc in ovarian cancer cells." (PMID 41584043, 2026). "Furthermore, ubiquitination assays demonstrated that USP7 knockdown significantly increased c-Myc ubiquitination in Sp1-overexpressing ovarian cancer cells." (PMID 41584043, 2026). "Furthermore, increased p21 level was observed after inactivation of USP7 by p5091 in ovarian cancer." (PMID 32922122, 2020). "Similarly, USP7 expression is strongly correlated with disease severity and lower overall patient survival in gliomas and epithelial ovarian cancer as well as in non-small cell lung cancer." (PMID 30319415, 2018). "Knockdown of USP7 inhibits the proliferation of ovarian cancer cells both in vitro and in vivo." (PMID 27780924, 2016). "In conclusion, using CDDO-Me as a probe, we identified USP7 as a novel target in ovarian cancer." (PMID 27780924, 2016). "Taken together, these data suggest that CDDO-Me inhibits USP7 activity in ovarian cancer cells." (PMID 27780924, 2016). "Using CDDO-Me as a probe, we found that USP7 is overexpressed in ovarian cancer cells." (PMID 27780924, 2016). "Subsequently, we examined the expression of USP7 in ovarian cancer samples by immunohistochemistry." (PMID 27780924, 2016). "Interestingly, the expression level of USP7 is inversely related to the degree of differentiation of ovarian cancer cells." (PMID 27780924, 2016). "Given that CDDO-Me is known to be effective against ovarian cancer cells, we speculated that CDDO-Me may target USP7 in ovarian cancer cells." (PMID 27780924, 2016).
ovarian carcinoma (continued). "In conclusion, we demonstrate that USP7 is a novel target of ovarian cancer cells; targeting USP7 may contribute to the anti-cancer effect of CDDO-Me." (PMID 27780924, 2016). "Furthermore, targeting USP7 contributed to CDDO-Me-induced ovarian cancer cell death, suggesting that USP7 is a novel drug target in ovarian cancer cells." (PMID 27780924, 2016). "Therefore, as USP7 regulates all of these proteins, the role of USP7 in ovarian cancer needs to be investigated." (PMID 25605410, 2015). "Targeting USP7 may represent a novel strategy to treat ovarian cancer." (PMID 27780924, 2016). "As recently demonstrated, USP7 specifically targets EZH2 in prostate and ovarian cancers, thus affecting EZH2-mediated angiogenesis." (PMID 41157055, 2025). "Therefore, we suspected that USP7 may be a target of CDDO-Me in ovarian cancer cells." (PMID 27780924, 2016). "However, the role of USP7 in ovarian cancer remains unclear." (PMID 27780924, 2016). "Experimental data confirmed that USP7 is upregulated in ovarian cancer cells compared to non-malignant controls and genetic silencing of USP7 via RNA interference significantly impaired tumor cell proliferation both in vitro and in murine xenograft models." (PMID 40732256, 2025). "In general, ovarian cancer tissues expressed significantly higher levels of USP7 compared with non-neoplastic tissue (p < 0.001)." (PMID 27780924, 2016). "As CDDO-Me could directly inhibit USP7 activity in vitro, we hypothesized that USP7 may be a novel target of CDDO-Me in ovarian cancer cells." (PMID 27780924, 2016). "Ovarian cancer tissues from non-neoplastic (n = 10), serous carcinoma (n = 46), mucinous adenocarcinoma (n = 15) and endometrioid carcinoma (n = 7) were stained with anti-USP7 antibodies." (PMID 27780924, 2016). "However, the possible role of USP7 in ovarian cancer is not yet clear." (PMID 27780924, 2016).
colorectal cancer (24 papers, 2017 to 2025). A primary or metastatic malignant neoplasm that affects the colon or rectum. "USP7 is also overexpressed in breast, cervical, and colorectal cancer, which is positively associated with the worse survival of patients with these diseases." (PMID 32300595, 2020). "To test this possibility, we examined the effect of USP7 inhibitor Almac4 on a panel of seven colorectal cancer cell lines with wild-type or mutated Wnt signaling pathway in colony formation assay." (PMID 31519875, 2019). "We further validate the predicted restoration effect of normal phenotypes through experiments with colorectal cancer organoids by controlling the reversion switch, USP7, a common target gene among the identified transcriptional factors." (PMID 39840939, 2025). "Inhibition of USP7 by P5091 significantly decreased spheroid sizes and numbers of colorectal cancer cells in a dose-dependent manner." (PMID 39346740, 2024). "By stabilising DDX3X, USP7 increases Wnt/beta‐catenin signalling, which has previously been demonstrated to be strongly correlated with colorectal cancer cell invasiveness." (PMID 38279869, 2024). "In summary, we suggested that USP7 regulated the stemness and potentially acted as a critical marker of CSCs in colorectal cancers." (PMID 39346740, 2024). "Knockdown of USP7 in colorectal cancer cells suppressed spheres formation and reduced cancer stem markers." (PMID 39346740, 2024). "Taken together, these results indicated that USP7 was highly expressed in CSC-enriched colorectal cancer cells." (PMID 39346740, 2024). "We next compared the protein level of USP7 between colorectal cancer stem-like cells and their counterpart adherent cells." (PMID 39346740, 2024). "USP7 has been previously confirmed to overexpress in colorectal cancer cells and neoplastic tissues." (PMID 39346740, 2024). "In colorectal cancer, USP7 can participate in the aberrant activation of the Wnt/β-catenin signaling through stabilization of the key transcriptional modulator β-catenin." (PMID 36186590, 2022). "From these experiments, we aimed to determine whether the inhibition of USP7 can lead to the reversion of colorectal cancer organoids." (PMID 39840939, 2025). "USP7 regulated cell growth, stemness and migration of colorectal cancer cells." (PMID 39346740, 2024). "Moreover, USP7 can up-regulate β-catenin, suggesting the potential of USP7 as a therapeutic target in colorectal cancer with a hyperactivated Wnt signaling, to suppress growth and overcome chemoresistance to Wnt inhibitors." (PMID 33967786, 2021). "In colorectal cancer cells, USP7 may regulate the deubiquitination of β-catenin, although the detailed binding mechanisms need to be further investigated." (PMID 32300595, 2020). "Our finding that USP7 inhibitor increases Wnt signaling brings up the concern that USP7 inhibitor might increase proliferation of colorectal cancers, since colorectal cancers often have dysregulated Wnt signaling." (PMID 31519875, 2019). "USP7 depletion significantly reduced proliferation of cancer cells and suppressed the self-renewal of CSC-enriched colorectal cancer cells." (PMID 39346740, 2024).
colorectal cancer (continued). "Moreover, studies have shown that USP7, USP10, USP33, and USP46 are all involved in the progression of colorectal cancer." (PMID 37371055, 2023).
viral infection (23 papers, 2013 to 2025). "The dysregulation of USP7 expressions or activity has been linked to several pathological conditions, including cancer, neurodegenerative and inflammatory diseases, and viral infections." (PMID 41157055, 2025). "USP7 has been implicated in the development and progression of various illnesses, including cancer, neurodegenerative disorders, viral infections, and inflammatory disease regression." (PMID 41157055, 2025). "Aberrant expressions or activity of USP7 have been implicated in a broad range of pathological conditions, including cancer, neurodegeneration, viral infections, and autoimmune disorders, consequently positioning it as an attractive pharmacological target." (PMID 41157055, 2025). "Among those DUBs, USP7 (herpesviral associated ubiquitin-specific protease [HAUSP]) was the first to be associated with viral infection, through interacting with herpesviral ICP0." (PMID 23555268, 2013). "The UPS is the primary cytosolic proteolytic machinery for the degradation of various proteins, including viral proteins, whereas viral proteins manipulate host proteins to reverse this process; for instance, the first identified DUB USP7 is associated with viral infection." (PMID 35638730, 2022). "To investigate the function of USP7 in EC activation, we generated stable overexpressing or knockdown ECs via lenti-virus infection, respectively." (PMID 40246841, 2025). "UBL domains assume a central role in USP7 regulation, thus affecting several physiological functions such as genome stability, epigenetic regulation, immune response, and viral infection." (PMID 41157055, 2025). "Next, we employed proximity ligation assay (PLA) to examine the impact of p8 on the interaction between OTUD4 and USP7 during viral infection." (PMID 40208866, 2025). "During viral infection, USP7 can regulate the stability and functionality of viral proteins, thereby influencing the replication and infection process of the virus." (PMID 39767641, 2024). "USP7 is the target of the herpes virus protein that enables the virus to escape and replicate efficiently, playing multiple roles in the process of viral infection." (PMID 38276639, 2023). "Strikingly, when we visualized viral infection by staining with DBP or USP7 during infection with the ΔSS virus, we noticed a large fraction of cells possessed a novel VRC morphology characterized by exceptionally large, round or donut-shaped bodies." (PMID 36095031, 2022). "The USP7 deubiquitinase reverses protein ubiquitination, and several groups have reported important proviral, as well as antiviral, roles of USP7 in virus infections (45, –, 50, 69)." (PMID 35254132, 2022). "USP7 is a conserved member of the deubiquitinase family involved in cellular stress, epigenetic silencing, cell survival, and viral infection." (PMID 26460617, 2015). "One such protein is the ICP0 protein of herpes simplex virus 1, which must bind USP7 in order to manipulate the cell in ways that enable efficient viral infection." (PMID 26046769, 2015). "Dysregulations of USP7 expression could lead to different pathological conditions including cancer, viral infections, inflammatory diseases, and neurodegenerative diseases." (PMID 41157055, 2025). "Furthermore, USP7 is involved in numerous aspects such as DNA damage repair, epigenetic regulation, and viral infections." (PMID 39767641, 2024).
viral infection (continued). "Indeed, Usp7 in Drosophila and its homolog HAUSP in mammals antagonize multiple E3 regulation of DNA damage response, transcription, epigenetic control of gene expression, immune response, and viral infection." (PMID 32531973, 2020). "Aberrant activation or overexpression of USP7 may promote oncogenesis and viral disease, making it a target for therapeutic intervention." (PMID 31114498, 2019). "In addition, USP7 is targeted by several viral proteins in order to promote cell survival and viral infection." (PMID 26046769, 2015). "USP7 removes ubiquitin molecules from substrates, preventing substrate degradation and resulting in their stabilization, which in turn modulates a wide range of cellular processes, such as the DNA damage response, immune response, cellular transcription, epigenetic inheritance, and viral infection." (PMID 40158127, 2025). "Interestingly, this interaction has been shown to stabilize ICP0 protein levels early during viral infection; however, later during the viral life cycle, ICP0 directs the degradation of USP7, a function that requires ICP0’s RING-finger domain and is regulated by ICP0 phosphorylation." (PMID 24852129, 2014).